IL10 (interleukin 10)
Diseases named in the same sentence as IL10 in open-access papers (continued):
Sharing a sentence is not in itself a finding about the gene and the disease.
tumor (continued). "miR-155 was previously shown to regulate inflammatory cytokine production (IL-6, IL-10 and TNFα) in tumor-activated macrophages via targeting CEBPB." (PMID 33540559, 2021). "IL-10 inhibits tumor growth by hindering several inflammatory and angiogenic factors, including vascular endothelial growth factor, IL-1β, TNF-α, and IL-6." (PMID 34361836, 2021). "Tumour tissue, tumour associated APCs, and macrophages express immune checkpoint molecules, such as IDO, and cytokines, such as IL-10, which also supress NK cell activity." (PMID 34835040, 2021). "IL-10, prostaglandin E2 (PGE2), and VEGF induced FasL upregulation in tumor endothelial cells to kill tumor-associated T cells, and anti-FasL attenuated this killing effect." (PMID 33859752, 2021). "The activation of the WNT/β-catenin signaling pathway has also been reported to be involved in the formation of an immune suppressive tumor microenvironment through the upregulation of IL-10." (PMID 34359568, 2021). "Distinct astrocytic phenotype exists in the tumor environment, which leads to a large release of anti-inflammatory cytokines such as TGFβ, IL10, and G-CSF through JAK/STAT pathway activation." (PMID 34084145, 2021). "Like M2 tumour-associated macrophages, MDSCs generate the cytokines IL-10 and TGF-β that can suppress anti-tumour tumour-infiltrating leukocytes, generate regulatory T cells in tumour, and convert dendritic cells into a regulatory phenotype." (PMID 33494138, 2021). "Increased levels of the anti-inflammatory cytokines IL-6 and IL-10 were also noted in co-cultures of single-cell tumor suspensions with PBMC and C-7." (PMID 34771609, 2021). "In the TME, infiltrating MDSCs rapidly differentiate into tumor-associated macrophages (TAMs) and produce a large number of immunosuppressive cytokines such as TGF-β and IL-10 to attract Tregs to the TME." (PMID 33718235, 2021). "In response, tumor-reactive astrocytes increase expression of CD274 as well as IL-10 and IFN-γ by reprogramming myeloid cells and upregulating PD-L1 and FasL." (PMID 34949203, 2021). "My findings strongly warrant the formulation of a clinical trial to test the anti-tumor efficacy of IL-10 in oncology patients in the near future." (PMID 33912464, 2021). "In the context of cancer, pegylated IL-10 has been shown to mediate tumor regression via tumor-infiltrating CD8+ T cell expansion and enhacement of immune checkpoint inihibitors." (PMID 34768810, 2021). "On the other hand, M2 or alternatively activated macrophages are typically activated by IL-4, IL-13 and IL-10, express IL-10 and favor wound healing as well as tumor development by suppressing anti-tumor T cell responses." (PMID 33494181, 2021). "Tumor cells typically promote polarization of TAMs toward M2 in TME, facilitating IL-10 production and tumor growth." (PMID 35111169, 2021). "Regulatory B-cells that express high levels of STAT3 have also been identified in the draining lymph nodes of lung cancer patients and promote tumor progression by inducing angiogenesis and immunosuppression via production of IL10." (PMID 34944848, 2021). "At the same time, IL-10 is an anti-inflammatory cytokine critical for dampening anti-tumor immune responses and upregulated by STAT3." (PMID 34956861, 2021). "Both LLC and B16F10 tumor models displayed the consistent results, IL-10 or Ad-hTERT treatment reduced tumor bulks mildly, compared to the negative control." (PMID 33717103, 2021). "In contrast, IL-10 is an acting immunosuppressive cytokine that is generally thought to support tumor growth and progression." (PMID 34257554, 2021). "According to some reports, IL-10 can be secreted by different types of cells, including numerous tumor cells, and almost all leukocytes." (PMID 33717103, 2021). "IL-10 downregulates the expression levels of L-selectin (CD62L) on naïve T-cells to prevent their migration to the tumor site, whereas TGF-β promotes the differentiation of TH17 cells (a subset of CD4 T-cells) into Tregs." (PMID 33919732, 2021).
tumor (continued). "My results showed that IL-10 and IL-15 administration led to reduction in tumor volume and increase in survival." (PMID 33912464, 2021). "Growing evidence has shown that the release of molecules, such as IL-6, IL-10 and IL-34 by TAMs, contributed to the acquisition of a chemo/radioresistant phenotypes in tumor cells." (PMID 34830817, 2021). "It demonstrated an additional regulatory mechanism of IL-10(+) B cells in the tumor microenvironment." (PMID 33679883, 2021). "The quantitative data of intravital imaging revealed that the capacity of CTLs' killing tumor cells in the liver was significantly increased from 1.09 ± 0.10 tumor cells/CTL/day to 2.24 ± 0.24 tumor cells/CTL/day after IL-10 blockade." (PMID 33391470, 2021). "EVs from mycoplasma-infected tumor cells induced B cell-dependent IL-10 production, which led to T cell inhibition." (PMID 33806053, 2021). "M2 macrophages are significantly increased in the BM of patients with MM relative to patients with MGUS, patients with SMM, and healthy donors; this effect appears to be largely mediated by increased levels of CXCL12 and IL-10 in the tumor microenvironment." (PMID 33717170, 2021). "M2 macrophages can secrete anti-inflammatory factors such as TGF-β and IL-10, and promote tumor growth and metastasis." (PMID 33936088, 2021). "Tregs release the immunosuppressive cytokine IL-10, inhibiting T cell proliferation and blocking anti-tumor immune responses, which further attenuates T cell cytotoxic activity and allows tumor growth." (PMID 34778089, 2021). "IL-10 mRNA transcripts can be isolated from tumor tissues including ovarian, breast, renal, lung, and skin cancer." (PMID 34806028, 2021). "For example, fish oil-fed mice possess a lower percentage of pro-tumor macrophages and interleukin (IL-10) expression and higher infiltrations of B cells and CD+ 8 T cells than coco butter-fed mice." (PMID 34742349, 2021). "Our findings showed that IL-10 concentration in the liver was significantly higher than that in the spleen, with a 21.9-fold in normal mice and 17.5-fold in tumor-bearing mice." (PMID 33391470, 2021). "As such, further investigations into the effects of IL-10 attenuation of CIAKI in a tumor-bearing model should be completed." (PMID 33805488, 2021). "The subgroup of M2d macrophages, also referred to as tumor-associated macrophages (TAMs), release IL-10 and vascular endothelial growth factor (VEGF), which stimulates angiogenesis and tumor growth." (PMID 33806053, 2021). "LAG-3+ Tregs in the TME secrete high levels of immunosuppressive cytokines, IL10 and TGFβ, which act to dampen the anti-tumour immune response and magnify Treg activity." (PMID 33401460, 2021). "Tumors are rich in IL-6 and IL-10, and the tumor-derived TLR-2 ligand versican can induce the overexpression of IL-6 and IL-10 receptors on DCs." (PMID 34290401, 2021). "The IL10+Ad-hTERT dramatically increased to seven or six times higher level of IFN-γ level compared with the PBS control group in LLC or B16F10 tumor-bearing mice respectively." (PMID 33717103, 2021). "As cytokines function as a critical role in the regulation of tumor immunity, we investigated the expression of two immunosuppressive cytokines including IL-10 and TGFB1." (PMID 34960256, 2021). "Taken together, IL-10 plays a dual role in eliciting immune responses with pro- and anti-tumour properties that need to be precisely regulated." (PMID 33401460, 2021). "For example, tumor immune surveillance was shown to be decreased in IL-10 knockout mice, whereas transgenic overexpression of IL-10 protected mice from carcinogenesis." (PMID 34769278, 2021). "Although, IL-10 has been broadly characterized as an immune suppressor, at higher concentrations IL-10 and PEGylated IL-10 (pegilodecakin) has shown to have properties that enhance cytotoxicity and proliferative capacity of tumor-specific CD8+ T cells." (PMID 33717081, 2021).
tumor (continued). "We observed that IL-10, Ad-hTERT, and IL-10+Ad-hTERT treatments increased the density of CD8+T cells in tumor microenvironment, compared to other treatments." (PMID 33717103, 2021). "This study provides the first evidence that IL-10 can directly kill cancer cells, thus demonstrating that IL-10 is a highly effective anti-tumor agent." (PMID 33912464, 2021). "It has been shown that PGE2 and TGF-β, both present in TDEs, are also critically involved in the abrogated function of tumor-associated DCs via the upregulation of ARG1 activity, IDO, and co-inhibitory molecule B7-H1 and B7-DC, as well as the IL-10 production." (PMID 34078376, 2021). "MDSCs impair tumor immunity by interacting with macrophages to increase IL-10 and decrease IL-12 production, driving a tumor-promoting type 2 response." (PMID 34765554, 2021). "An earlier study showed that CD137-CD137L (4-1BB-4-1BBL) interaction impairs NK cell anti-tumor activity in humans via induction of IL-10 and TNF release from AML cells, which allowed AML cells to evade being eliminated by NK cells." (PMID 34372571, 2021). "IL-10 is a key immunoregulator, suppressing T cell functions and inducing Tregs development, thus favoring tumor immune evasion and the lower frequency of T cells observed in pre-treatment patients." (PMID 34830209, 2021). "Other than inhibiting T-cell activation, IL-10 can boost the expression of PD-1 on tumor-infiltrated DCs and make tumor cells more resistant." (PMID 34206425, 2021). "The overexpression of IL-10 and TGF-β associated with decreased IFN-γ and IL-12 production can reduce host tumor immunity and indirectly promote tumor growth." (PMID 34436224, 2021). "Crosstalk between M2 macrophages and Tregs, immunosuppressive factors of the TME (TGF‐β, IL‐10, IDO1), and tumor antigen PD‐L1 cause CD8+ T‐cell inactivation and contribute to inefficient CD8+ T‐cell response priming." (PMID 33252831, 2021). "Studies have shown that tumour-derived IL-4, IL-5, IL-6, IL-10, and IL-13 can stimulate TAM polarization towards TAM-M2." (PMID 34141479, 2021). "In some solid tumor models, depletion of the gut microbiota leaded to a significant increase in IFN-γ-producing T cells and a decrease in IL-17A and IL-10-producing T cells, thereby reduced tumor burden." (PMID 34307157, 2021). "In summary, we concluded that four experimental groups showed cytokine stimulation, but these effects of the vaccines gradually vanished over time, but IL-10, as an immunoregulatory cytokine, remained in the tumor environment to inhibit antitumor function." (PMID 33792840, 2021). "In the present study, Th2-polarized and anti-inflammatory cytokine IL-10 either secreted by T lymphocytes in the splenocytes or peritoneal macrophages in the tumor microenvironment were correlated with Fas mRNA expression levels in the treated PC-3 cells." (PMID 33807287, 2021). "IL10 production by tumor cells down-regulates HLA-I and HLA-II on tumor cells and HLA-II on antigen-presenting cells (APCs), inhibiting antigen presentation becoming an escape mechanism from immune surveillance." (PMID 34447383, 2021). "One of the major functions of TAMs is suppressing the T-cell mediated anti-tumor immune response via expression of IL-10 and transforming growth factor β (TGFβ)." (PMID 35366268, 2021). "A series of cytokines and inflammatory mediators, such as interleukin-10, transforming growth factor-beta, and prostaglandin E2, are produced in the tumor microenvironment." (PMID 34796109, 2021). "Promote Tregs to produce IL-10, thereby inhibit T cell responses and assist immunosuppression and tumor progression." (PMID 34737750, 2021). "Once chronic inflammation is established in the tumor, Th cells promote the M2 polarization of macrophages by secretion of a myriad of cytokines including IL-4, IL-10, and IL-13." (PMID 33530455, 2021).
tumor (continued). "Bregs can also induce the polarization of naïve CD4+T cells into both FOXP3+ Treg cells and IL-10-producing Tr1 cells, modulating cancer progression and increasing tumor metastasis." (PMID 34164398, 2021). "Tumor-infiltrating LY6G MDSCs from orthotopic liver tumors treated with sorafenib dramatically increased CD4 T cells expressing IL-10 and TGF-and decreased CD8 T cell cytotoxicity." (PMID 34869376, 2021). "Compared with other doses, 5 μg/injection of IL-10 showed the strongest effect of inhibiting tumor growth." (PMID 33717103, 2021). "Despite various roles, IL-10's capability in downregulating MHC I leads the tumour cells, NK-sensitive." (PMID 34336101, 2021). "Immune modulating cytokines (TGF-β, IL-10, IL-17, and IL-23) facilitate tumor development, while others (IFN-γ, TNF-α, GM-CSF, IL-2, IL-6, IL-17, and IL-12) promote immune surveillance and delay its growth." (PMID 34518597, 2021). "IL-10 was traditionally thought to promote tumour proliferation by inhibiting immune responses, with studies revealing positive correlation between IL-10 levels and tumour proliferation in various malignancies." (PMID 34944729, 2021). "This IL-10 trap-based nanotechnology significantly inhibited tumor growth and improved survival in an orthotopic TNBC 4T1 model." (PMID 34944738, 2021). "MDSCs are actively drawn and activated in the tumors by various secretory products like PGE2, VEGF, GM-CSF, IL-6, TNF-α, IL-10, and IL-1β elaborated by TIICs, CAFs, and the tumor cells themselves." (PMID 33996630, 2021). "Recent data suggest that TIMs show the largest amount of PD-L1 molecules, promoted by IL-10 secreted by tumour cells." (PMID 33804731, 2021). "Conversely, TAMs can secrete chemokines and cytokines, particularly IL-6, IL-8, and IL-10, that are involved in tumor growth, angiogenesis, tumor invasion, and the depression of immunity." (PMID 33916915, 2021). "In tumor-bearing rats, the IL-10 concentration was 1.7 times higher and the IL-17 concentration was less than half that of intact rats." (PMID 34443443, 2021). "Increased Wnt signalling is also thought to enhance the regulatory state of DCs by producing IL-10 and IL-12 in the tumour microenvironment, thereby promoting the antigen priming process of CD8 + T cells." (PMID 34321580, 2021). "WNT5a can also specifically activate the TLR/MyD88/p50 pathway in bone marrow monocytes and promote the synthesis of anti-inflammatory cytokines such as IL-10 and the tolerance phenotype, thus forming an immunosuppressive tumor microenvironment." (PMID 34565373, 2021). "Il‐10 is a cytokine that induces an immune response and an anti‐inflammatory microenvironment that promotes tumor growth by helping tumor cells evade immune surveillance." (PMID 33626234, 2021). "Uptake of tumor-derived exosomes also alters the cytokine secretion (IL-6, IL-1β, IL-10 and TNFα) of macrophages thereby facilitating several pro-tumoral functions." (PMID 34638420, 2021). "In mouse tumour models, IL-10 inhibits tumour growth by increasing the expression of IFN-γ in CD8+ T cells." (PMID 34565443, 2021). "In vitro and in vivo studies have demonstrated that IL-10+ Bregs induced by mouse tumor cells are able to reduce IFN-γ production by antigen-specific CD8+ and CD4+ T cells as well as NK activation." (PMID 33995344, 2021). "MDSCs also suppress T cell anti-tumor actions via programmed death-ligand 1 (PD-L1), arginase (Arg-1), interleukin-10 (IL-10) and transforming growth factor beta (TGF-β)." (PMID 34531850, 2021). "Interleukin 10 (IL-10) is a cytokine that has been recognized as a central player in cancer biology with its ability to inhibit anti-tumor T cell responses." (PMID 34769278, 2021). "The anti-inflammatory cytokine IL-10 has been shown to induce a skewing from a Th1 immune-phenotype (with anti-tumor activity) to a predominant Th2 response (with pro-tumor activity)." (PMID 33806300, 2021).
tumor (continued). "Chemoresistant GBM cells promote the suppression of TLR4 expression in tumor-infiltrating macrophages that release cytokines such as IL-6 and IL-10 and support a tumor-promoting ME." (PMID 34646780, 2021). "It has been indicated that PD-1 hi B cells are the main subtype of Bregs in human HCC and operate through an IL10-dependent pathway to induce T cell dysfunction, thereby creating conditions conducive to tumor progression." (PMID 34235074, 2021). "Alternatively, Th2 cells can contribute to tumor immune escape through production of IL-10 and IL-4, both of which inhibit the response of Th1 cell effectors, the verification response of inflammatory cells, antigen promotion, and T cell proliferation." (PMID 35082830, 2021). "Administration of IL-10 was also found to suppress tumor volume and prolong the survival of AJ mice injected with NXS2 cells." (PMID 33912464, 2021). "Prolonged inflammation leads to loss of MHC I expression on tumor cells and can be attributed to the effect of an immunosuppressive cytokine TGF-β, IL-10, and the epidermal growth factor (EGF) which are secreted in the TME." (PMID 34858978, 2021). "STAT3 signalling between tumour cells, immune cells and the tumour microenvironment is mediated by factors, including IL‐6, IL‐10 and VEGF." (PMID 33382511, 2021). "Various cells (AIMs, microglia, astrocytes) in tumor microenvironment can produce high level of immunosuppressive cytokines like transforming growth factor β (TGFβ) and interleukin-10 (IL-10) in response to inflammatory stimuli." (PMID 34675919, 2021). "In the context of murine tumor model, we conducted the in vivo study to evaluate the effects of IL-10 on Ad-hTERT viroimmunotherapy." (PMID 33717103, 2021). "miR-21 is a negative regulator for TLR4 to activate NF-κB and decrease IL-10 production by targeting a pro-inflammatory tumor suppressor PDCD4." (PMID 33618723, 2021). "With the stimulation of 17β-estradiol, ERβ promotes the differentiation of Treg, which dominates the secretion of IL-10 as well as TGF-beta and down-regulate the activity of CD8+ T cell, causing the suppression of T cell-induced tumor immunocytotoxicity." (PMID 34098945, 2021). "IL10 is clearly a tumor-promoting cytokine and is responsible for augmenting immunosuppression in the TME and providing angiogenic stimuli to facilitate tumor growth." (PMID 34064000, 2021). "Hypoxia-induced tumor-derived cytokines, such as IL-10 and transforming growth factor-beta, can induce tumor-associated macrophages to differentiate into M2 macrophages with immunosuppressive effects." (PMID 33737938, 2021). "IL-10 blocking antibodies drive accumulation of tumor-infiltrating lymphocytes (TILs), release of granzyme B, and tumor cell necrosis in an in vitro human CRC culture system." (PMID 34489941, 2021). "We observed increased expression of the effector cytokines TNF-α and IL-2 concomitantly with decreased secretion of IL-10 in culture supernatants of tumor-infiltrating leukocytes treated ex vivo with activin-A." (PMID 34548096, 2021). "IL-10 not only plays an important role in modulating T cell functions but also plays critical roles in modulating anti-tumor or pro-tumor effects by other immune cells that are abundant in the tumor microenvironment." (PMID 34769278, 2021). "Regulatory B cells (Breg cells), a novel subset of B lymphocytes, appear to facilitate tumor growth and progression via the production of IL-10 to suppress the activity of CD8+ T cells in squamous carcinoma." (PMID 34447376, 2021). "Recruitment of MDSC in the TME aid in this suppression of TH immune cells, where TNF-α, IL-1, IL-6, colony stimulating factor 1 (CSF-1), IL-8, IL-10, and type I interferons can also play a role in the regulation of TH immune response to tumor cells." (PMID 34012451, 2021). "Meanwhile, tumor vascular ECs also can secrete immunosuppressive cytokines (e.g. interleukin 10 (IL-10), prostaglandin E2 (PGE2) and VEGF)." (PMID 34930293, 2021).